EBF1 (EBF transcription factor 1)
Diseases named in the same sentence as EBF1 in open-access papers (continued):
Sharing a sentence is not in itself a finding about the gene and the disease.
cancer (continued). "Moreover, ZNF521 knockdown‐mediated elevation of EBF1 expression resulted in downregulation of AKR1B1 and subsequent inhibition of cancer cell proliferation, migration, and invasion." (PMID 36397644, 2023). "EBF1 inhibits IL-6 expression leading to the inhibitions of Jak-STAT, RAS and MAPK signaling pathways as well as COX-2 and MMP-9 expressions resulting in the inhibition of cancer progression." (PMID 33854627, 2021). "The transcription factor EBF1 is an interaction partner of the TET2 gene and is involved in the regulation of DNA methylation in a tissue- and sequence-specific mode of IDH1-mutant cancers." (PMID 27863437, 2016). "Then, the functional roles of EBF1 were examined in CCA cells in order to confirm that restored EBF1 expression can suppress tumorigenic, stemness and oxidative stress-resistant properties in the cancer cells, suggesting possible application of epigenetic therapy for CCA treatment." (PMID 33854627, 2021). "Our findings identify EBF1 as novel interaction partner of TET2, confirm IDH mt-mediated hypermethylation to be a recurrent phenomenon in unrelated types of cancer, and have identified tissue- and cancer- specific effectors as key drivers, and potential therapeutic targets." (PMID 23863747, 2013). "Finally, although we did not examine EBF1 because of lack of enrichment of its binding sites in TET-regulated accessible regions of the genome, EBF1 has been shown to increase both chromatin accessibility and DNA demethylation in B progenitor cells, and to interact with TET2 in a cancer cell line." (PMID 27869616, 2016).
infection (5 papers, 2018 to 2025). The state of being infected such as from the introduction of a foreign agent such as serum, vaccine, antigenic substance or organism. "Wnt signaling molecules, genes associated with inflammation and infection, such as EBF1, TIMP2, COL4A3, TNF, and the candidate gene for schizophrenia, i.e., ABCA13, have been identified as PTB biomarkers through the multiple target studies, though their mechanisms remain unclear." (PMID 38391647, 2024). "At the late infection stage, ethylene response was drastically repressed: seven out of nine highly expressed DEGs were significantly down-regulated, especially EBF1/2 DEGs, whose expression was reduced by more than 20 times." (PMID 34685435, 2021). "On day 5 post infection, EBF1 showed lower occupancy of all of its sites on the LPKOw genome, while the virus did not alter EBF1 binding to host genome loci at any time." (PMID 29462212, 2018). "Activation of this whole genome region was severely delayed in EBNA-LP mutant infections, and this correlated with the delayed recruitment of EBF1, EBNA2 and – albeit less dramatically – RBPJK to the viral genome." (PMID 29462212, 2018). "Overall, scRNA-seq data confirm that T2 LCLs are much more likely to enter fully lytic infection than T1 LCLs, and suggest that both viral and cellular factors (including NFATc1, IRF4 and EBF1 levels) contribute to this difference." (PMID 35472072, 2022). "Recruitment of EBF1 both to EBNA2-dependent LMP and Cp promoters and to the EBNA2-independent EBER/oriP loci was delayed in LPKOw infection." (PMID 29462212, 2018). "Furthermore, both knockouts demonstrated that EBNA-LP is crucial for establishing and stabilizing the viral transcription program after infection, and for facilitating the recruitment of EBNA2 and the host protein EBF1 to the incoming virus genome." (PMID 29462212, 2018).
cardiovascular disease (4 papers, 2012 to 2024). "EBF1 is reported to be associated with human cardiovascular disease, but its roles are unclear in heart." (PMID 39239522, 2024). "This discovery, coupled with the association between EBF1 and cardiovascular diseases highlighted by genome-wide association studies (GWAS) 19-22, led us to speculate that EBF1 can play a role in human cardiac development and the specification of cardiomyocytes." (PMID 39239522, 2024). "These genes, in particular, EBF1 given its potential biological plausibility, serve as novel candidate loci for cardiovascular disease and should be further evaluated." (PMID 22369142, 2012). "Our study results provide new biological insights into EBF1 variants and CAD risk and may identify novel targets for the prevention of cardiovascular disease." (PMID 28183271, 2017). "Using this approach, we have identified four candidate genes (EBF1, PPP2R2B, PRELID2, and SPOCK1) that may represent novel cardiovascular disease risk genes mediated through LDL cholesterol pathways." (PMID 22369142, 2012). "Interestingly, studies of knockout mice have identified a role for EBF1 in metabolism, a cardiovascular disease related phenotype." (PMID 22369142, 2012).
blood cancer (2 papers, 2022 to 2024). "This review mainly focuses on the effects of EBF1, PAX5, and MYC on B cell development and their association with hematologic neoplasms." (PMID 38318177, 2024). "In short, as pivotal TFs in B cell development, the abnormalities of EBF1, PAX5, and MYC result in hematologic tumors." (PMID 38318177, 2024). "Given that the aberrant expression and function of EBF1, PAX5, and MYC contribute to hematologic neoplasms, therapies targeting them may shed light on these diseases." (PMID 38318177, 2024). "To test whether enforced FOXO1 expression is sufficient to induce EBF1, IRF4, or PAX5 expression in non-B-lineage blood cancer cells, we next transduced lentivirus encoding FOXO1 into the AML cell lines HEL and THP1, which express negligible levels of EBF1, FOXO1, IRF4, and PAX5." (PMID 36282572, 2022).
metabolic disease (2 papers, 2018 to 2021). A congenital disorder (due to inherited enzyme abnormality) or acquired (due to failure of a metabolically important organ) disorder resulting from an abnormal metabolic process. "Over the last several years, evidence has accumulated that various genetic alterations in the EBF1 locus may represent a risk factor for metabolic disease." (PMID 33732506, 2021). "Finally, our finding that Ebf1 expression is significantly altered by HP/LC maternal diet is suggestive of a metabolic disorder and dysregulation of neural development, as previous studies have linked this gene with childhood obesity and neuronal differentiation." (PMID 30619467, 2018).
neurological disease (2 papers, 2005 to 2019). "Two genetic markers within the EBF1 gene have been found associated with this neurological disease, indicative either of their causative role or that of some other polymorphism in linkage disequilibrium with them." (PMID 16255771, 2005). "In this work we aimed at testing the Early B-cell Factor (EBF1) gene as a functional and positional candidate risk factor for this neurological disease." (PMID 16255771, 2005).
hematologic cancers (1 paper, 2025). "Recent findings indicate that early B-cell factor 1 (EBF1), a transcription factor essential for cell differentiation and maturation, exhibits a comparable yet more intricate and variable mechanism of action in solid tumors compared to hematological cancers." (PMID 40508012, 2025).
respiratory disease (1 paper, 2025). "The EBF1 protein has demonstrated roles in respiratory disease as it can downregulate the proteasome subunit β type 1 (PSMB1) protein during porcine reproductive and respiratory syndrome virus (PRRSV) infection to indirectly increase disease susceptibility." (PMID 40822650, 2025).
EBF1 also shares sentences with these, for which no sentence is quoted: neuroblastoma (3 papers); acute leukemia (2); B cell lymphopenia (2); B-cell acute lymphoblastic leukaemia (2); hematologic malignancies (2); Hyperglycemia (2); alcohol abuse (1); Alzheimer disease (1); Autoimmunity (1); brain diseases (1); central obesity (1); Cirrhosis (1); diabetic kidney disease (1); encephalitis (1); gastrointestinal stromal tumour (1); gestational diabetes (1); head and neck cancer (1); hypospadias (1); immune disease (1); intestinal cancer (1); intestinal disease (1); kidney damage (1); lung adenocarcinoma (1); lymphoid leukemia (1); medulloblastoma (1); myeloproliferative neoplasm (1); nasopharyngeal carcinoma (1); orthostatic hypotension (1); osteoporosis (1); pancreatic cancer (1).
A further 7 diseases each share a sentence with EBF1 in 1 paper.